FGFR4 (fibroblast growth factor receptor 4)
Diseases named in the same sentence as FGFR4 in open-access papers (continued):
Sharing a sentence is not in itself a finding about the gene and the disease.
tumor (continued). "Mechanically, we revealed that dysregulation of FGFR4 led to activation of the AKT/RYR2 axis and the following tumor proliferation, invasion, and lipid metabolism reprogramming in TNBC." (PMID 39658878, 2024). "Dysregulated FGFR4 activates the AKT/RYR2 axis, leading to tumor proliferation, invasion, and altered lipid metabolism in TNBC." (PMID 39658878, 2024). "Lenvatinib prevents tumor angiogenesis through inhibition of VEGFR-1, -2, and -3, and also blocks the proliferation of tumor cells through inhibition of FGFR-1, FGFR-2, FGFR-3, & FGFR-4, PDGFRα, RET, and c-KIT." (PMID 38622735, 2024). "Although it has been reported that pharmacologically use of FGF15/19 leads to liver cell growth and neoplasia, NGM282, a full FGFR4 agonist, due to its inability to activate STAT3 pathway, it lacks tumor-promoting activity in mice." (PMID 38971765, 2024). "To model heterogeneous expression of tumor antigens in an in vivo model, we established bilateral orthotopic xenografts with RH30 FGFR4-KO (right leg) and CD276-KO (left leg)." (PMID 39043633, 2024). "Using RNA-Seq data for human RMS tumors (n = 98) and cell lines (n = 33), we confirmed that FGFR4 and CD276 were highly expressed in RMS compared to 147 normal tissues with significant heterogeneity among tumor samples." (PMID 39043633, 2024). "Fibroblast growth factor receptor 4 (FGFR4), as a member of the FGFR family, is involved in tumorigenesis and tumor progress in various tumors." (PMID 39658878, 2024). "In Rh4-tumor bearing mice, CD276/FGFR4 Dual-CAR T cells showed a similar complete eradication as CD276.V-CAR T cells." (PMID 37924157, 2023). "Among the FGFR family members (FGFR1, FGFR2, FGFR3, and FGFR4), only FGFR2 was significantly upregulated in PanCK(+) tumor epithelial cells at the EOCC tumor invasive margin compared to the LOCC tumor invasive margin in NGDSP analysis." (PMID 37964075, 2023). "Overall, our data indicated that the combination of FGFR4 and EZH2 inhibitors can significantly inhibit tumor growth both in vitro and in vivo, which would supply new literatures for the development of clinical treatment strategies for HCC." (PMID 37085881, 2023). "The combined use of FGFR4 inhibitors and sorafenib suppresses FGFR4/ERK signaling and enhances tumor suppression in mice." (PMID 37610679, 2023). "Previous finding demonstrates that FGF19 and FGFR4 are coexpressed in CRC and facilitate tumor growth." (PMID 36923538, 2023). "Based on extensive in silico and wet lab analyses of GBM tissues, tumor explants, and GSC models, we have identified FGFR4 mRNA and protein overexpression in a distinct GBM subgroup, which was traced back to the original patient tumor samples by IHC." (PMID 35484633, 2022). "Consistently, qPCR confirmed higher rate of dEx2FGFR4/FGFR4 in response to EIF4A3‐silencing in both cell lines treated in vitro, as well as in the Hep3B‐induced in vivo tumours formed in nude mice." (PMID 36419260, 2022). "Preclinically, FGF401 showed in vivo phospho-FGFR4 IC90 at 52.1 nM and anti-tumor efficacy was driven by a fraction of time above this IC90, or depending on the trough concentration levels." (PMID 35655320, 2022). "For example, FGFR4 phosphorylates and activates STAT3 to promote tumor-extrinsic immune evasion in various cancers." (PMID 35562334, 2022). "It exhibited outstanding anti-tumor activity in FGF19-expressing HCC cell lines with FGF19 amplification and intact FGFR4, as well as xenograft models with an intact FGFR4/KLB signaling pathway." (PMID 36080304, 2022). "In vivo, co-targeting FGFR4 and CDK4/6 also showed marked inhibition of tumor growth than single agent treatment." (PMID 35463335, 2022). "FGF401 showed anti-tumor activity in HCC cell lines expressing FGF19 and FGFR4 on their surface like Huh7, SNU878, and Hep3B and xenografts." (PMID 36080304, 2022).
tumor (continued). "Combining tumor-normal and inter-tumor analyses, we identified overexpressed targets including PDGFRB, FGFR4, ERBB2/3, CDK6 kinases and MFAP5, HMCN1, and Hsp proteins in HCC, many of which showed low frequencies of genomic and/or transcriptomic aberrations." (PMID 35433463, 2022). "Besides, variant rs351855‐G/A can lead to germline FGFR4 G388R substitution, subsequently expose a membrane‐proximal STAT3‐binding site and trigger STAT3 signalling cascade, which can accelerate cancer progression and also contribute to tumour‐extrinsic immune evasion." (PMID 33655556, 2021). "The expression of FGF19 was similar to FGFR4 in more than half of the cases, and a significant correlation was noted between the expression of FGF19 and FGFR4 in tumor tissues (r = 0.601, p < 0.001)." (PMID 33674622, 2021). "Our analyses revealed that the combined use of sorafenib or regorafenib with a selective FGFR4 inhibitor suppressed FGFR4-mediated ERK signaling, thereby producing additional anti-tumor effects." (PMID 33674622, 2021). "In FGF19+FGFR4+ HCC and FGF19−FGFR4− HCC groups, 39.4% and 23.1% of patients had vascular invasion or tumor satellite nodules, respectively." (PMID 33674622, 2021). "The three novel MET, FGFR4, and ERBB3 isoforms were predicted to be initiated from promoters distinct from their annotated TSSs (51 kb away (MET), 438 bp (FGFR4), 248 bp (ERBB3), and upregulated in tumor samples to a greater degree from their known isoforms." (PMID 33482911, 2021). "Cav-1 and Cav-2 were reported to be regulated by FGFR4 and CDH2 and, also, correlated with tumor progression, invasion and metastasis." (PMID 33809909, 2021). "It has been demonstrated that miR-491-5p suppresses tumor growth in certain cancers and can indirectly inhibit FGFR4, thus reducing the SNAIL level and weakening EMT-induced tumor migration." (PMID 33981224, 2021). "In that study, it was observed that when the FGF19- FGFR4 interaction occurs in TAF, FGFR4 can phosphorylate β-catenin, which, in turn, can be translocated into the nucleus where can mediate the tumor-stroma interactions, facilitating the metastatic process." (PMID 34200439, 2021). "High FGFR4 phosphorylation characterized a luminal B PDX model and treatment with BLU9931 significantly decreased tumor growth." (PMID 34344433, 2021). "FGF401 can act synergistically with vinorelbine to inhibit tumor growth and promote tumor apoptosis by inhibiting the FGF19/FGFR-4 signaling pathway." (PMID 34724890, 2021). "CXCL5, ELN, JUN, and FGFR4 were highly expressed in normal tissues, while PLAU, RNASE7, JAG1, SPP1, and TNFRSF18 were highly expressed in tumor tissues." (PMID 32699529, 2020). "We determined that its expression in PDAC positively correlated with larger tumor size and more advanced tumor stage, and that BLU9931, a selective FGFR4 inhibitor, reduced PDAC cell proliferation and invasion while promoting their senescence." (PMID 33066597, 2020). "FGFR4 is a member of the FGFR family, contains tyrosine kinase domains, and plays a critical role in embryonic development, tissue repair, tumor angiogenesis, and tumor progression." (PMID 32154250, 2020). "Strong FGFR4 immunoreactivity was seen in the cancer cells in 67 of 136 (49%) PDAC samples and high FGFR4 expression correlated with larger primary tumor size and more advanced stages of the cancer (p < 0.001)." (PMID 33066597, 2020). "While FGFR4 was highly expressed in the JN-DSRCT-1 cell line, we observed variable expression in the tumor samples." (PMID 32703985, 2020). "For example, in a small size cohort study, high FGFR4 expression correlated with tumor progression and survival in both diffuse and intestinal GC, whereas high expression of FGFR1 and 2 correlated with tumor progression and survival only in diffuse type GC." (PMID 31242658, 2019). "Ablation of up‐stream driver fibroblast growth factor receptor 4 (FGFR4) effectively inhibits inflammation and neoplasia in PM‐exposed murine colons." (PMID 31179224, 2019).
tumor (continued). "We determined the FGFR4 Gly388Arg genotype and the mRNA expression of FGFR4 and N-cadherin in a cohort of 65 NSCLC tumors using DNA and RNA extracted from FFPE tumor samples." (PMID 29402970, 2018). "High FGFR4 expression was frequently found in DGC and even in IGC and was significantly related to tumor progression and metastasis in both types of GC." (PMID 28056982, 2017). "In conclusion, high FGFR4 expression correlated with tumor progression and survival in both DGC and IGC, whereas high expression of FGFR1 and 2 correlated with tumor progression and survival in only DGC." (PMID 28056982, 2017). "From existing data it seems that patients with tumours with detectable expression of FGF19, FGFR4 and Klothoβ would benefit from such an approach and approximately one third of all patients with HCC are expected to meet these criteria." (PMID 28943626, 2015). "In a study of FGF-8 expression in OC, this cytokine was localized to tumor cells, whereas its receptors FGFR1, FGFR2, and FGFR4 were expressed by tumor cells, and to lesser extent, in stromal cells." (PMID 24860785, 2014). "In HCC cells FGF19 signals through the FGFR4/β-klotho complex, which is also frequently up-regulated in human HCC tissues and is emerging as a good candidate anti-tumor target." (PMID 23285165, 2012). "Thus, the FGFR4 Arg388 genotype may be used as an additional risk factor for tumour progression with respect to invasion; however, it does not seem to be a good prognostic factor for disease outcome." (PMID 16721364, 2006). "Therefore, chimeric antigen receptor (CAR) T cells have been engineered to target FGFR4 and CD276, thereby successfully reducing T cell exhaustion, enhancing T cell persistence, and restoring a robust anti-tumor immune response." (PMID 41007114, 2025). "Both genes are implicated in PitNET pathophysiology but act through distinct biological pathways: FGFR4 regulates growth factor signaling, while PTTG1 functions as a proto-oncogene influencing chromosomal stability, cell cycle progression, and tumor proliferation." (PMID 41573212, 2025). "We investigated whether treatment with FGFR4 and CXCR3 inhibitors can suppress tumor growth and CAF differentiation." (PMID 40447617, 2025). "Although our study did not identify statistically significant associations between FGFR4 variants and PA, these null results are informative as they suggest that these FGFR4 variants may have a limited role in PA pathogenesis, helping to refine current genetic models of this tumor type." (PMID 40806692, 2025). "Finally, dual inhibition of FGFR4 and CXCR3 suppressed tumor growth, accompanied by CAF downregulation." (PMID 40447617, 2025). "Other groups have previously proposed tumor suppressive functions for both HNF1A and FGFR4." (PMID 40731412, 2025). "Our findings also complement and challenge previous reports by confirming that genetic variation in FGFR4 does not uniformly contribute to tumor behavior across different tumor types, underscoring the tissue-specific nature of FGFR4 involvement." (PMID 40806692, 2025). "Furthermore, selective FGFR4 inhibition with BLU9931 synergised with lenvatinib, enhancing its anti-tumour efficacy in both HCC cell lines and PDOs." (PMID 40715090, 2025). "Early-phase trials of selective FGFR4 inhibitors (e.g., fisogatinib/BLU-554; roblitinib/FGF401) showed activity in FGF19-positive or FGFR4/KLB-positive tumours, validating pathway dependence but not yet yielding a registrational success." (PMID 41301037, 2025). "Dual inhibition of FGFR4 and CXCR3 suppresses tumor growth through CAF downregulation." (PMID 40447617, 2025). "Although FGFR4 was expressed in fetal tumor organoids, FGF19 was not present in our culture medium, indicating that it was not essential for maintaining organoid culture in the presence of other growth factors." (PMID 39567475, 2024).
tumor (continued). "However, FGFR4.8HTM.BBz-CD276.8HTM.BBz BiCisCAR, which shares the same CD8 HTM and 4-1BB CSD for both FGFR4 and CD276 CAR cassettes, only delayed tumor progression compared to mock T-cells in an RH30 orthotopic xenograft model." (PMID 39043633, 2024). "We found that replacing the CD8 hinge and transmembrane domain (HTM) and the 4-1BB co-stimulatory domain (CSD) of our recently reported clinical grade FGFR4 targeting CAR with CD28 HTM and CSD resulted in increased cytotoxicity in vitro and improved anti-tumor efficacy in vivo." (PMID 39043633, 2024). "There were two instances of the FGFR1 gene amplification and one tumor with FGFR4 gene extra copies; however, no increase in mRNA expression of the corresponding gene was observed in these samples." (PMID 39596194, 2024). "Silencing FGFR4 reduces cellular adhesion in CRC, while knocking out FGFR4 in CRC by CRISPR-Cas9 upregulates E-cadherin and downregulates EMT mediators to reduce the tumor metastasis ability." (PMID 39796710, 2024). "In NPC, MSC-derived exosomes are associated with elevated expression of fibroblast growth factor (FGF)-19, enhancing tumour growth, migration, and metastasis through the activation of the FGF19-fibroblast growth factor receptor 4 (FGFR4)-dependent ERK signaling cascade and promotion of EMT." (PMID 39450176, 2024). "The oncogenic potential of WT FGFR4 is supported by the findings that FGFR4 knockdown reduced tumour growth in a human RMS cell line and lung metastases in a RMS mouse model, and WT FGFR4 overexpressing mouse-myoblasts induced tumour formation in vivo." (PMID 37130917, 2023). "To investigate whether FGFR4 and EZH2 inhibitors could synergistically repress tumor growth in vivo, we first administered Roblitinib and CPI-169 alone or in combination in the zebrafish HCC primary tumors." (PMID 37085881, 2023). "In the first 252 tumours published from ZERO, overexpression of FGFR genes was reported in 16 tumours (6.3%), dominated by FGFR4 overexpression in fusion positive RMS (9 tumours), in which FGFR4 overexpression is a known molecular feature and is directly regulated by PAX3-FOXO1." (PMID 37130917, 2023). "In BCX.080, a model with FGFR3 and FGFR4 RNA overexpression and without a detectable genomic alteration, futibatinib had modest tumor growth inhibition without significantly prolonging EFS." (PMID 37980453, 2023). "While the FGFR4 inhibitor BLU-554 or the METTL16 GapmeR ASO alone was able to inhibit CCA cell growth, we found that combinational use of both the FGFR4 inhibitor BLU-554 and the METTL16 GapmeR ASO exhibited more tumor inhibitory effect." (PMID 37817227, 2023). "Moreover, treatment with an FGF receptor 4 (FGFR4) inhibitor, BLU9931, to block FGF19 function recapitulates the effects of HMGA1 or FGF19 silencing, decreasing tumor growth and stroma formation in orthotopic models." (PMID 36919699, 2023). "The results indicated that the RNA level of FGFR2 (p<0.05) and FGFR4 (p<0.001) was considerably higher in tumor tissues compared to the matched adjacent non-tumor tissues." (PMID 36147913, 2022). "FGFR4 can not forecast trends for the markers of tumor stage, node stage, and vascular infection, but it can predict their occurrence." (PMID 36532586, 2022). "Moreover, western blotting assessments of FGFR4 and p‐STAT3 in xenograft tumour lysates revealed that, consistent with the in vitro results, DCZ0415 inhibited the expression of these proteins." (PMID 35194944, 2022). "Analyzing data from the primary HCC tumor cohort, we also observed a lack of correlation between FGFR4 protein or mRNA expression and FGF19 gene expression levels." (PMID 35433463, 2022). "Our data also showed that co-targeting FGFR4 and CDK4/6 could significantly inhibit tumor growth in both the mouse models." (PMID 35463335, 2022).
tumor (continued). "Tumours with low levels of FGFR4 showed the highest basal-like/squamous scores regardless of the FGFR1 status (either high or low); indeed, the signature scores between the FGFR4lowFGFR1high and FGFR4lowFGFR1low were not significantly different." (PMID 35963908, 2022). "Also, deletions of JAK2, CD274 and MYD88 genes, and amplification of FGFR4 and NPM1 genes, are also involved in clinical trials for other tumor types." (PMID 33668731, 2021). "Consistent with the findings in vitro, SHP099 at its maximum tolerated dose of 100 mg per kilogram bodyweight (mpk) daily (QD) had no anti-tumor effect while the FGFR4 inhibitor FGF401 dosed at 30 mpk twice every day (BID) effectively suppressed tumor growth." (PMID 32076487, 2020). "Second, FGFR4-targeted vincristine-loaded liposomes bound specifically to RMS cells and were internalized by the receptor, demonstrating the potential for active drug delivery to the tumor." (PMID 33182650, 2020). "There was no tumor formation observed in colonic tissues of AOM/PM treated Fgfr4−/− mice by histological analysis." (PMID 31179224, 2019). "Silence of FGFR4 in radio-resistant HT29 decreased the cell survival after irradiation, while its overexpression in radio-sensitive SW480 conferred the stronger DNA damage repair ability on the tumor cells." (PMID 30112378, 2018). "Furthermore, our study explored the effects of the polymorphic genotypes of FGFR4 on the clinicopathological status of OSCC, which includes TNM clinical staging, tumor size, lymph node involvement, and cell differentiation." (PMID 29221201, 2017). "It has been shown that FGFR4 has a non-substitutable role in modulating FGF19 activity to liver such as tumor growth and development." (PMID 26498355, 2016). "However, only FGFR1 was expressed at high level, with a mean transcript expression of 187 RPKM in NRH-LS1 (and 143 in tumor B), compared to 0.3, 47, and 7.9 for FGFR2, FGFR3 and FGFR4, respectively." (PMID 27409346, 2016). "This study extends our discovery that hepatic FGFR4 signaling underlies control of cholesterol to bile acid metabolism by showing the local and systemic effects on tumor development in a tissue where FGFR4 is normally not directly at play." (PMID 24279986, 2013). "In this study, we hypothesized that the FGF19/FGFR4 system is activated in patients with HCC and is correlated with the aggressiveness of the tumor." (PMID 22309595, 2012). "FGFR4 staining was not significantly greater in the membranes of tumor cells as compared to those of cells from corresponding noncancerous tissue." (PMID 22309595, 2012). "This was confirmed by the higher amount of CD-31-positive vessels within the tumours with positive FGFR4 protein expression as opposed to FGFR4-negative tumours." (PMID 16721364, 2006). "A global Phase I clinical trial involved 38 patients with FGFR4-driven HCC who had undergone multiple chemotherapy treatments; six patients (16%) achieved objective responses, 26 patients (68%) had disease control, and 18 patients (49%) experienced a reduction in tumor burden." (PMID 41328353, 2026). "The activation of the FGF19/FGFR4 signaling pathway increases the infiltration of TAMs and myeloid-derived suppressor cells (MDSCs) while decreasing the accumulation of CD8+ T cells, leading to the formation of an immunosuppressive microenvironment that favors tumor progression." (PMID 41328353, 2026). "Notably, in this study, cerebral hemangioblastomas had a higher likelihood of positive staining for FGFR4, suggesting that the expression characteristics of FGFR may vary depending on tumor location." (PMID 40393028, 2025). "In addition, co-targeting FGFR4 and CDK4/6 could significantly inhibit FGF19-driven LUSC proliferation and tumor growth in vitro and in mouse models." (PMID 35463335, 2022).